RMI1 (RecQ mediated genome instability 1)
Description:
Essential component of the RMI complex, a complex that plays an important role in the processing of homologous recombination intermediates to limit DNA crossover formation in cells. Promotes TOP3A binding to double Holliday junctions (DHJ) and hence stimulates TOP3A-mediated dissolution. Required for BLM phosphorylation during mitosis. Within the BLM complex, required for BLM and TOP3A stability.
Synonyms: BLAP75; C9orf76; FLJ12888; FAAP75
Tractability: Small molecule: a structure with a bound ligand is known. PROTAC: UniProt records ubiquitination sites on it; ubiquitination databases record sites on it.
Gene: Protein-coding gene on chromosome 9 (83,980,355 to 84,004,078, forward strand). Ensembl gene ENSG00000178966.
Subcellular location: Nucleus
Subcellular location (Human Protein Atlas): Nuclear bodies; Nucleoplasm
Pathways (Reactome):
DNA Repair: HDR through Homologous Recombination (HRR); HDR through Single Strand Annealing (SSA); Homologous DNA Pairing and Strand Exchange; Presynaptic phase of homologous DNA pairing and strand exchange; Processing of DNA double-strand break ends; Resolution of D-loop Structures through Holliday Junction Intermediates; Resolution of D-loop Structures through Synthesis-Dependent Strand Annealing (SDSA)
Disease: Defective HDR through Homologous Recombination Repair (HRR) due to PALB2 loss of BRCA1 binding function; Defective HDR through Homologous Recombination Repair (HRR) due to PALB2 loss of BRCA2/RAD51/RAD51C binding function; Defective homologous recombination repair (HRR) due to BRCA1 loss of function; Impaired BRCA2 binding to PALB2; Impaired BRCA2 binding to RAD51
Cell Cycle: G2/M DNA damage checkpoint
Gene Ontology:
Molecular function: protein binding; nucleotide binding
Biological process: double-strand break repair via homologous recombination; resolution of DNA recombination intermediates
Cellular component: nuclear body; nucleoplasm; RecQ family helicase-topoisomerase III complex; nucleus
Genetic constraint (gnomAD): Loss-of-function variants: 36 observed, 47.68 expected, observed/expected ratio (o/e) 0.75, 90% interval 0.58 to 1. The upper end of that interval is the gene's LOEUF score, 1, which puts it in group 4 of 6, group 1 being the genes least tolerant of losing a copy. Missense variants: 665 observed, 740.63 expected, observed/expected ratio (o/e) 0.9, 90% interval 0.84 to 0.96. Synonymous variants: 246 observed, 260.4 expected, observed/expected ratio (o/e) 0.94, 90% interval 0.85 to 1.05.
Homologues: Orthologues: chimpanzee RMI1 (99% identical), macaque RMI1 (95% identical), pig RMI1 (83% identical), rabbit RMI1 (80% identical), guinea pig RMI1 (79% identical), mouse Rmi1 (72% identical), rat Rmi1 (70% identical), tropical clawed frog rmi1 (43% identical), zebrafish rmi1 (30% identical), Caenorhabditis elegans rmh-2 (21% identical), Caenorhabditis elegans rmh-1 (21% identical).
Diseases named in the same sentence as RMI1 in open-access papers:
RMI1 is named in the same sentence as 19 diseases in open-access papers, as found by Europe PMC text mining. Sharing a sentence is not in itself a finding about the gene and the disease. The quoted sentences say what the papers report.
Bloom syndrome (9 papers, 2008 to 2025). Bloom syndrome (BSyn) is a rare chromosomal breakage syndrome characterized by a marked genetic instability associated with pre- and postnatal growth retardation, facial sun-sensitive telangiectatic erythema, increased susceptibility to infections, and predisposition to cancer. "RMI1 plays an important role in DNA repair and is closely associated with many human diseases, including tumors, obesity, and Bloom syndrome 37-39." (PMID 33976734, 2021). "One tumour showed an alteration in RecQ Mediated Genome Instability 1 (RMI1, associated with Bloom Syndrome and Baller-Gerold Syndrome)." (PMID 34680387, 2021). "Mutations on BLM and the TRR (TOP3A/RMI1/RMI2) subcomplex have been linked to Bloom syndrome (BS) or BS-like genetic disorders, predisposing individuals to cancer development." (PMID 40846865, 2025). "In contrast, future studies in animal models in which the RPA-binding motifs in BLM and RMI1 are mutated may be informative in elucidating which function(s) of BLM are required to prevent the various pathologies with Bloom syndrome, with possible future therapeutic consequences for patients." (PMID 33500419, 2021). "RecQ-mediated genome instability protein 1 (RMI1) is a member of an evolutionarily conserved Bloom syndrome complex, which prevents and resolves aberrant recombination products during HR, thereby promoting genome stability." (PMID 38007566, 2023). "Therefore, it is suggested that individuals in the Bloom syndrome registry lacking molecular diagnosis may have causative variants in other genes as RMI1, RMI2, or TOP3A genes with the overlapping phenotypic manifestation." (PMID 37052241, 2023). "Here, we demonstrate that the Bloom syndrome complex contains three RPA-binding motifs, two in BLM and one in RMI1." (PMID 33500419, 2021). "Bloom DNA helicase (BLM) combines closely with DNA topoisomerase IIIα (Top3A), RecQ-mediated genome instability protein 1 (RMI1), and RecQ-mediated genome instability protein 2 (RMI2) to form a conserved Bloom syndrome (BS) complex, which is vital for maintaining genome stability." (PMID 38007566, 2023). "Interestingly, the recruitment of FANCM requires its direct interaction with Bloom syndrome complex composed of BLM helicase, Topoisomerase 3α, RMI1 and RMI2; as well as the helicase activity of BLM." (PMID 28058110, 2016). "We also suspect that a similar pathway is promoted by FANCM in humans, and in this regard it is interesting to note that the FA core complex copurifies with the Bloom syndrome complex, which contains the orthologs of Rqh1 (=BLM), Top3 (=Top3α), and Rmi1 (=BLAP75)." (PMID 18851838, 2008).
breast carcinoma (4 papers, 2009 to 2024). "RMI2 is also upregulated in breast cancer and SNPs in BLM and RMI1 were associated with breast carcinoma." (PMID 33662042, 2021). "In order to test this hypothesis we analysed in this study polymorphisms in the RMI1, TOP3A and BLM, and their association with cancer risk in available case-control materials, namely AML/MDSs (acute myeloid leukemia and myelodysplastic syndromes), malignant melanoma, and bladder and breast cancer." (PMID 19432957, 2009).
acute myeloid leukemia (2 papers, 2009 to 2022). Acute myeloid leukemia (AML) is a group of neoplasms arising from precursor cells committed to the myeloid cell-line differentiation. "RMI1 is suggested to be involved in leukemia (including acute myeloid leukemia) where reduced expression of RMI1 and other critical genes seems to result in disease." (PMID 35935937, 2022). "In this study we have studied 26 tagged single nucleotide polymorphisms (tagSNPs) in RMI1, TOP3A, and BLM and their associations with cancer risk in acute myeloid leukemia/myelodysplatic syndromes (AML/MDS; N = 152), malignant melanoma (N = 170), and bladder cancer (N = 61)." (PMID 19432957, 2009).
bladder cancer (2 papers, 2009 to 2024). "The SNP rs296887 (RMI1) was significantly associated with increased cancer risks for AML/MDS, as well as for malignant melanoma, but not with risk for bladder cancer." (PMID 19432957, 2009).
epilepsy (2 papers, 2023 to 2025). A brain disorder characterized by episodes of abnormally increased neuronal discharge resulting in transient episodes of sensory or motor neurological dysfunction, or psychic dysfunction. "Of note, expression of RMI1 was associated with GGE in both TWAS (P = 4.0 × 10−10) and SMR (P = 5.2 × 10−8), as well as with ‘all epilepsy’ (TWAS P = 1.3 × 10−6; SMR P = 2.6 × 10−6)." (PMID 37653029, 2023).
Fanconi anemia (2 papers, 2021). Fanconi anemia (FA) is a hereditary DNA repair disorder characterized by progressive pancytopenia with bone marrow failure, variable congenital malformations and predisposition to develop hematological or solid tumors. "Among this, we found 3 mutations related to the Fanconi anemia (FA) DNA repair pathway (RMI1, PALB2, FANCI)." (PMID 34549727, 2021). "Mutations in genes that regulate DNA repair (RMI1, PALB2, FANCI) were identified that were related to the Fanconi anemia DNA repair pathway." (PMID 34549727, 2021).
Obesity (2 papers, 2021 to 2023). Accumulation of substantial excess body fat. "RMI1 is upregulated by obesity and high-glucose conditions and plays a role in maintaining genome integrity during replicative stress." (PMID 36969166, 2023).
COVID-19 (1 paper, 2022). A disease caused by infection with severe acute respiratory syndrome coronavirus 2. "A summary data-based Mendelian randomization (SMR) analysis and a transcriptome-wide association study (TWAS) were performed for the severe COVID-19 dataset, and seven novel genes for severe COVID-19 were identified, including CCR5, CCR5AS, IL10RB, TAC4, RMI1, and TNFSF15." (PMID 36483456, 2022).
glioma (1 paper, 2021). A benign or malignant brain and spinal cord tumor that arises from glial cells (astrocytes, oligodendrocytes, ependymal cells). "Thus, knockdown of hsa_circ_0091581 inhibits glioma growth in vivo, and this effect is associated with miR-1243-5p and RMI1." (PMID 33976734, 2021). "The expression of RMI1 in clinical samples indicated that RMI1 was upregulated in glioma tissues compared with the level in ANTs." (PMID 33976734, 2021). "The results of the luciferase reporter and RNA immunoprecipitation assays indicated that the mechanism of the effects of hsa_circ_0091581 on glioma cells involves sponging miR-1243-5p to regulate RMI1." (PMID 33976734, 2021). "Our data indicate that RMI1 is upregulated in glioma tissues and cell lines, and qRT-PCR, western blot, and functional assays demonstrated that RMI1 is a functional target of miR-1243-5p." (PMID 33976734, 2021). "The results of the rescue experiments indicated that hsa_circ_0091581 regulates proliferation, migration, and invasion of glioma cells by targeting RMI1 in a miR-1243-5p dependent manner." (PMID 33976734, 2021). "Overall, our study is the first to report that hsa_circ_0091581 promotes glioma proliferation, migration, and invasion by targeting the miR-1243-5p/RMI1 axis that may be a potential target for glioma treatment." (PMID 33976734, 2021). "Finally, in vivo assays suggested that hsa_circ_0091581 can inhibit glioma growth, and this effect was mediated by miR-1243-5p and RMI1." (PMID 33976734, 2021). "In summary, hsa_circ_0091581 can promote glioma proliferation, migration, and invasion via the hsa_circ_0091581/miR-1243-5p/RMI1 axis and may be a novel therapeutic target in glioma." (PMID 33976734, 2021). "Thus, our study determined the role of hsa_circ_0091581/miR-1243-5p/RMI1 in glioma and suggests that this axis may be a novel therapeutic target in glioma." (PMID 33976734, 2021). "Additionally, the expression of RMI1 was higher in glioma cells than that in NAs." (PMID 33976734, 2021). "However, the role of RMI1 in glioma has not been reported previously." (PMID 33976734, 2021).
malignant melanoma (1 paper, 2009). "As mentioned, we have previously studied the Ser455Asn polymorphism in RMI1 and found an association between increased risk of AML/MDS and malignant melanoma for variant carriers." (PMID 19432957, 2009).
Miscarriage (1 paper, 2021). A pregnancy that ends at a stage in which the fetus is incapable of surviving on its own, defined as the spontaneous loss of a fetus before the 22th week of pregnancy. "In CG2, whose female partner suffered a miscarriage at 8 weeks, RNA analysis of spermatozoa identified 3 imbalanced genes involved in important DNA-binding transcription factor activity (RMI1) and embryogenesis (CBX2 and TGFB3)." (PMID 33877510, 2021).
pulpitis (1 paper, 2025). Inflammation of the dental pulp. "For the phenotype Pulpal and apical diseases, two other loci in chromosomes 2 (near BCL11A) and 9 (near RMI1), and for the phenotype Pulpitis, three other loci in chromosomes 1 (near PDE4B), 9 (near NR4A3), and 17 (near VMP1 and TUBD1) were identified." (PMID 40701953, 2025).
Stroke (1 paper, 2023). Sudden impairment of blood flow to a part of the brain due to occlusion or rupture of an artery to the brain. "MIER1, a transcriptional repressor, and RMI1, a DNA repair protein, were also positively correlated with stroke severity." (PMID 36803375, 2023).
cancer (4 papers, 2009 to 2025). A tumor composed of atypical neoplastic, often pleomorphic cells that invade other tissues. "It has been reported that the RMI1 gene polymorphisms were associated with the risk of cancer, but further studies are needed to investigate." (PMID 34549727, 2021). "Thus, genetic variants of BLM and proteins that form complexes with BLM, such as TOP3A and RMI1, might affect cancer risk as well." (PMID 19432957, 2009). "During exposure to ionizing radiation exposure (4 and 8 Gy), RMI1 prevents and resolves abnormal recombination products during HR to maintain genomic stability in both normal and cancer cell lines." (PMID 39425547, 2025). "The protein level of RMI1 in 293 T cells was similar to that in cancer cells." (PMID 38007566, 2023). "The protein levels of RMI1 were relatively low in normal cell lines (IMR90 and MRC5) while relatively high in cancer cells (U2OS, HeLa, and H460), with the exception of 293 T cells." (PMID 38007566, 2023).
tumor (3 papers, 2016 to 2021). "CHAF1A and RMI1 expression are remarkably higher in tumor tissues of GC when compared with normal samples (all P < 0.0001)." (PMID 33785812, 2021). "The fact that these five genes (MTHFD2, EIF4E, RMI1, CAV1 and HIF1A) are all very relevant in tumor biology further emphasizes a role of Wig-1 in the regulation of cell cycle and cell proliferation, as well as tumor onset, progression and metastasis." (PMID 26672765, 2016). "One of these tumours had a concomitant alteration in BARD1, and a second in BRCA1 and RMI1." (PMID 34680387, 2021).
RMI1 also shares sentences with these, for which no sentence is quoted: myelodysplastic syndrome (2 papers); Baller-Gerold syndrome (1); infection (1); leukemia (1).